AR (androgen receptor)
Diseases named in the same sentence as AR in open-access papers (continued):
Sharing a sentence is not in itself a finding about the gene and the disease.
renal carcinoma (17 papers, 2015 to 2025). A carcinoma arising from the epithelium of the renal parenchyma or the renal pelvis. "There are sex differences in the lung metastasis of renal carcinoma, with high expression of the androgen receptor (AR) closely linked to this process." (PMID 40387186, 2025). "AR positivity was associated with a significantly better progression-free survival (PFS) compared to AR negativity in renal cancer [S45]." (PMID 25595907, 2015). "Increased expression of proteins involved in sex steroid inactivation (AKR1C1, AKR1C2, AKR1C3, AKR1B10) in DIO1 re-expressing renal cancer cells might indicate decreased local production of androgens, which have been linked to proliferation of renal and other cancers expressing androgen receptor." (PMID 29272308, 2017). "In nude mouse models, increased AR expression significantly enhances lung metastasis of renal cancer." (PMID 40387186, 2025). "Recently, attention has been drawn to the regulatory effect of the AR via its interaction with non-coding RNAs in the progression of various tumor types, including breast, lung, prostate, and renal cancers." (PMID 39585048, 2024). "The lncRNA termed suppressing androgen receptor in renal carcinoma (SARCC) showed promising results both in vitro and in vivo." (PMID 39585048, 2024). "The presented results can be the basis for further investigation of the role of AR-FL and AR-SVs in renal carcinoma to determine the effect of presently accepted therapies on the localization and activity of the SVs." (PMID 34440475, 2021). "AR, an androgen receptor, suppresses bone metastasis of renal cancer and acts as a valuable feature in prognosis in ccRCC." (PMID 35004689, 2021). "Recent study also showed evidence that LSD1 could regulate renal cancer cell growth through epigenetic control of androgen receptor transcription factors." (PMID 35633893, 2022). "Notably, SPOP not only can be functionalized as a tumor suppressor by targeting androgen receptor for degradation, but also as an oncoprotein in renal cancer, resulting in activation of androgen receptor driven pathways." (PMID 34838022, 2021). "In recent years, with the deepening of epigenetic research, the epigenetic regulatory mechanisms of renal cancer, especially DNA methylation, are often used to predict the survival time of renal cancer, including DAB2IP, RCVRN, CRHBP, AR, and CDO1." (PMID 32733620, 2020). "This regulation is likely direct, as AR is specifically recruited to the DHX9 promoter in LNCaP cells, as previously reported in renal carcinoma cells, while AR inhibition under androgen deprivation or enzalutamide treatment caused repression of DHX9 expression." (PMID 35590370, 2022).
testicular cancer (17 papers, 2014 to 2026). A primary or metastatic malignant neoplasm that affects the testis. "The GCTC-specific miRNA, called miR-371a-3p, is responsible for the regulation of AR expression and is also used as diagnostic marker for testicular cancer according to the S3 guidelines of the testicular cancer diagnostics." (PMID 35453608, 2022). "Men with androgen insensitivity syndrome due to AR gene mutations have a higher risk of developing testicular cancer." (PMID 26421011, 2015). "This would enable further understanding of the role of the AR gene and polymorphism frequency in the onset of testicular cancer in patients of different ethnic origins." (PMID 26421011, 2015). "Moreover, androgens showed an inhibitory effect on the growth of seminomatous neoplastic cells both in vitro and in vivo, and a case–control study found that specific polymorphisms of the androgen receptor gene were associated with testicular cancer risk." (PMID 40801896, 2026). "To investigate the reason for the inhibition of testosterone and its receptor AR in the development of testicular cancer, we identified genes whose expressions correlate negatively with AR (PCC < −0.3 and FDR < 0.05)." (PMID 39796131, 2024). "AR signaling plays important roles in regulating tumorigenesis and metastasis in several cancers including, kidney, lung, breast, and testis cancer." (PMID 33082888, 2020). "In this study, we investigated the effects of androgen/AR signaling on testicular cancer cell growth in vitro and in vivo." (PMID 27144435, 2016). "We used testicular cancer cell lines as a human testicular cancer model to investigate the role of androgen/AR signaling in human testicular cancer." (PMID 27144435, 2016). "The gene expression signature of AR in the testicular cancer cells may suggest that androgen/AR functions in SE cells." (PMID 27144435, 2016). "These aspects lead us back to the crucial role played by the length of the polymorphic segment in AR function; a change in the number of repeats can lead to various disorders and, above all, is a risk factor for testicular cancer that should not be ignored." (PMID 26421011, 2015). "The relationship between USP26 and AR in testicular cancer requires further study." (PMID 24922532, 2014). "The risk of testicular cancer (TC) is markedly increased in subjects with androgen insensitivity, and previous studies have proposed that GGN and CAG repeats in androgen receptors (AR) could be related to the risk of TC." (PMID 26885616, 2016). "Because the androgen/AR signal has a critical role in normal organogenesis and spermatogenesis in testes, it is reasonable to think that insufficiency of the signal may lead to initiation of testicular cancer." (PMID 27144435, 2016). "In 2008, a case-control study investigated the correlation between testicular cancer and p,p-DDE, an environmental pollutant that is an androgen receptor antagonist." (PMID 26421011, 2015).
Huntington disease (16 papers, 2007 to 2026). Huntington disease (HD) is a rare neurodegenerative disorder of the central nervous system characterized by unwanted choreatic movements, behavioral and psychiatric disturbances and dementia. "Extended CAG trinucleotide repeats (TNR) in the genes huntingtin (HTT) and androgen receptor (AR) are the cause of two progressive neurodegenerative disorders: Huntington’s disease (HD) and Spinal and Bulbar Muscular Atrophy (SBMA), respectively." (PMID 36585400, 2022). "The history of polyglutamine diseases dates back approximately 20 years to the discovery of a polyglutamine repeat in the androgen receptor of SBMA followed by the identification of similar expansion mutations in Huntington's disease, SCA1, DRPLA, and the other spinocerebellar ataxias." (PMID 25309920, 2014). "In this review, we underscore the role of the androgen receptor in regulating lipid and cholesterol levels during neurodegenerative disorders (Alzheimers, Parkinson’s, multiple sclerosis, and Huntington’s disease)." (PMID 41340464, 2023).
invasive carcinoma (16 papers, 2009 to 2025). A carcinoma that is not confined to the epithelium, and has spread to the surrounding stroma. "At this age, prostates of PRN mice contained primarily HGPIN, as well as foci of AR-/INSM1- invasive carcinoma." (PMID 34099734, 2021). "The AR positivity rate in triple-negative PLC cases in the present study (92.8%) was clearly higher than that previously reported in triple-negative invasive carcinoma of NST, which ranged from 17.7% to 41%." (PMID 32697770, 2020). "Several studies have reported AR positivity rates in patients with triple-negative invasive carcinoma of NST." (PMID 32697770, 2020). "The inductive UGM dictated NHPrE1/EV cells to form benign glandular structures, whereas the NHPrE1/AR recombinants developed invasive carcinomas." (PMID 27611945, 2016). "In contrast, the invasive carcinomas formed by the NHPrE1/AR grafts were weakly positive for cytokeratin 8/18 and strongly positive for p63, a prostate basal cell marker." (PMID 27611945, 2016). "Further molecular studies are needed to determine the mechanisms by which high-grade PIN induced by chronic bacterial infection and inflammation progresses towards an invasive carcinoma independently of circulating androgens and AR." (PMID 19844236, 2009). "Furthermore, in 2 cases, AR monosomy was observed in the normal ductal cells surrounding the invasive carcinoma." (PMID 33534004, 2021). "In our study, most of the dimorphic ICs were Grade I invasive carcinoma and low grade DCIS; this may be associated with a high incidence of AR expression." (PMID 28965222, 2018). "Inherited differences in AR CAG length might influence the transition from DCIS to invasive carcinoma, perhaps by modulating the function of AR in breast tissue." (PMID 22988495, 2012). "Amongst the TNBC that were AR negative, invasive carcinoma NST accounted for 27of 38 cases (71.1%), metaplastic carcinoma 10 of 38 cases (26.3%) and invasive lobular carcinoma 1of 38 cases (2.6%)." (PMID 36405944, 2022). "The predominant histologic type was invasive carcinoma (NST) in both AR positive and AR negative categories." (PMID 36405944, 2022). "The expression of the androgen receptor was lower than that of non-special luminal invasive carcinomas, about 15–18% of NEBC." (PMID 32414120, 2020). "Additionally, most ER-/PR-/AR+ invasive carcinomas with apocrine differentiation exhibited negative expression of TRPS1 and GATA3." (PMID 40822238, 2025). "Final pathology revealed a 1.7 × 1 × 1 cm invasive carcinoma with apocrine morphology, clear margins and five negative sentinel nodes; IHC showed ER/PR/HER2 negativity, AR strongly positive (90%), and low proliferation (Ki-67 8%)." (PMID 41245818, 2025).
invasive ductal carcinoma (16 papers, 2012 to 2025). "Emerging studies indicate that AR positivity is significantly higher in TNBC‐invasive lobular carcinoma compared to TNBC‐invasive ductal carcinoma." (PMID 40703006, 2025). "Histopathological examination confirmed invasive ductal carcinoma (grade II) with infiltrative growth, ER/PR/AR positivity (90%), and TRPS1 expression, confirming mammary origin." (PMID 40978063, 2025). "Positive expression of AR plays an important guiding role in the diagnosis of ductal adenocarcinoma." (PMID 38263473, 2024). "Conversely, some reports suggest that AR may participate to the development of invasive ductal carcinoma by repressing E-cadherin expression." (PMID 26862856, 2016). "Apocrine breast carcinoma is a rare subtype of invasive ductal carcinoma, which is primarily defined by morphological features such as abundant eosinophilic and granular cytoplasm, and shows frequent expression of the androgen receptor (AR)." (PMID 25070172, 2014). "Another frequent pitfall is misclassification as invasive ductal carcinoma NST when AR immunostaining is not performed in ER/PR negative cases." (PMID 41245818, 2025). "This study aimed to investigate the prognostic value of AR in HER2+ nonmetastatic breast invasive ductal carcinoma (IDC) and its relationship with the immune microenvironment." (PMID 37085500, 2023). "We have previously shown that nuclear expressions of DYRK2 and HSF1 correlate in TNBC and quadruple-negative breast cancer (QNBC: ER, PR, HER2, and androgen receptor negative) subtypes of invasive ductal carcinoma patient tumours." (PMID 36622366, 2023). "For tumors without metastases, ductal invasive carcinomas were reported in 84.8% of cases, with grade 2 in 51.5%; ER-positivity in 99.3%; PR positivity in 81.9%; AR positivity in 96.9% and low expression of Ki67 in 61.1%." (PMID 35454911, 2022). "One study observed up-regulation of AR-213 and AR-650 phosphorylation in invasive ductal adenocarcinoma; however patient survival was not investigated." (PMID 28415597, 2017). "The frequency of infiltrating ductal carcinoma decreased (not significantly) across increasing categories of AR expression (89%, 80%, 81%, and 78%)." (PMID 23241075, 2012).
kidney cancer (16 papers, 2016 to 2026). Primary or metastatic malignant neoplasm involving the kidney. "Aside from kidney cancer, our results reveal that high AR activity is associated with poor survival in patients with UCEC and SKCM (OS endpoint)." (PMID 41486951, 2026). "Further, it was shown that high expression of AR was associated with better survival rates supporting a tumor suppressor role for AR in kidney cancer." (PMID 33778495, 2021). "Clearly, a more rigorous investigation of the nuances of AR biology in kidney cancer is needed to understand the clinical significance of high versus low AR activity in this disease." (PMID 41486951, 2026). "In summary, all these reports provide novel insight to understand the role of androgen and AR in the pathogenesis of kidney cancer and identify AR as a potential therapeutic target to suppress RCC progression and improve patient’s outcomes." (PMID 34572815, 2021). "Follow-up studies showed that lysine-specific histone demethylase 1 (LSD1), an epigenetic co-regulator of AR, knocked-down in kidney cancer cells led to a slower growth and decreased migration ability of the cells in vitro and in a xenograft mouse model." (PMID 34572815, 2021). "To analyse AR function in kidney cancer, we selected Caki-2 cells among several RCC cell lines because there are reports of AR expression in this cell line." (PMID 32847068, 2020). "We therefore designed a co-treatment strategy, using pargyline with AR inhibitor enzalutamide, which showed an additive effect on reducing kidney cancer cell proliferation and migration." (PMID 32847068, 2020). "We focused on androgen receptor (AR) regulation by its epigenetic co-regulator lysine-specific histone demethylase 1 (LSD1) in kidney cancer development." (PMID 32847068, 2020). "In this study, we showed that LSD1 regulated AR activity in kidney cancer cells and demonstrated that pargyline, used as a LSD1 inhibitor, reduced the kidney cancer cell proliferation rate and metastatic ability." (PMID 32847068, 2020). "This is true for papillary and clear-cell RCCs which suggests a broader role of AR signaling in tumorigenesis of kidney cancer." (PMID 29108248, 2017). "In kidney cancer, however, the expression of AR is negatively correlated with cancer development." (PMID 32847068, 2020). "In our study, we specified AR as the target of LSD1 inhibitors in kidney cancer cells." (PMID 32847068, 2020). "In fact, cellular localization and interaction with other co-factors may affect AR activity in kidney cancer." (PMID 32847068, 2020). "LSD1 knock-down in kidney cancer cells decreased expression of AR target genes." (PMID 32847068, 2020). "Taken together, cellular localization and the regulation of AR by co-factors may play a more important role than its expression in kidney cancer development." (PMID 32847068, 2020). "We found that pargyline, known as a LSD1 inhibitor, can reduce AR activity in kidney cancer cells." (PMID 32847068, 2020). "However, our data suggest that targeting LSD1 and AR may be a good treatment option for kidney cancer patients screened for high-level AR expression." (PMID 32847068, 2020). "Next, we assessed whether LSD1 modulation affects AR activity in kidney cancer cells." (PMID 32847068, 2020). "Moreover, several reports showed that AR has functions in kidney cancer progression." (PMID 32847068, 2020). "Therefore, the role of AR in kidney cancer development received less attention." (PMID 32847068, 2020). "Moreover AR expression has been recognized in kidneys and kidney cancer." (PMID 29108248, 2017). "In kidney cancer, LSD1 interacts with AR and regulates downstream target genes of AR through demethylation of H3K9, and inhibition of LSD1 increases the sensitivity of kidney cancer cells to drugs." (PMID 40028036, 2025). "The epigenetic control of AR co-regulates lysine-specific histone demethylase 1 (LSD1) in kidney cancer development, and the LSD1 inhibitor can reduce growth of kidney cancer cells." (PMID 35565241, 2022).
kidney cancer (continued). "We found that LSD1 binds to AR target genes including KLK2, KLK3, and TMPRSS2 in kidney cancer cells, and confirmed that the binding decreased in LSD1 shRNA-expressing cells." (PMID 32847068, 2020). "However, the fact that most AR proteins in normal kidney tissues are in the cytoplasmic fraction raised the possibility that AR amounts may not be directly linked with its actual function in kidney cancer." (PMID 32847068, 2020). "Here, we focused on the role of LSD1 in the regulation of AR activity in kidney cancer growth and metastasis, and explored the possible use of LSD1 chemical inhibitors for kidney cancer treatment." (PMID 32847068, 2020). "Next, we analysed AR activity by quantifying levels of its target genes IGF1R and MYC in enzalutamide and/or PG-treated kidney cancer cells." (PMID 32847068, 2020). "In summary, we showed the epigenetic regulatory function of LSD1 on AR activity in kidney cancer development and migration, and the possible use of LSD1 inhibitors in kidney cancer therapeutics." (PMID 32847068, 2020). "To investigate LSD1 function as an AR regulator, we expressed control or LSD1 short hairpin RNA (shRNA)s using lentiviral system in Caki-2 kidney cancer cells." (PMID 32847068, 2020). "Dihydrotestosterone promoted kidney cancer cell proliferation by activating the STAT5 pathway via androgen and glucocorticoid receptors (AR and GR), which could be attenuated by AR and GR knockdown." (PMID 34199002, 2021). "Meanwhile, it has been reported that KDM1A can regulate kidney cancer cell growth via epigenetic control of AR transcription factors and that KDM1A inhibitors may be good candidate drugs for treating kidney cancer." (PMID 34925656, 2021). "Moreover, the binding of AR to target gene promoters was reduced and histone methylation status was changed in LSD1 knock-down kidney cancer cells." (PMID 32847068, 2020). "As we only focused on AR activity and the regulation of its downstream genes, it might be interesting to study the effect of LSD1 inhibitors on the activity of other transcription factors, and co-treatment with their inhibitors in kidney cancer." (PMID 32847068, 2020).
lung adenocarcinoma (16 papers, 2014 to 2026). A carcinoma that arises from the lung and is characterized by the presence of malignant glandular epithelial cells. "Further, microarray analysis of the AR transcriptome in the lung adenocarcinoma cell line A549 demonstrated that the AR regulates pathways involved in, e.g., oxygen transport, DNA repair and DNA recombination." (PMID 36560732, 2022). "Forced overexpression of GHSROS in the A549 lung adenocarcinoma cell line decreased AR and PPP2R2C expression (Student’s t-test, P ≤ 0.0001)." (PMID 33585078, 2021). "Similarly, LSD1 inhibitors can resensitize CRPC to AR blockade, but in lung adenocarcinoma, LSD1 inhibition disrupts EGFR and KRAS pathways with variable effects on tumor growth." (PMID 41601922, 2026). "Despite being well characterized as suitable cell lines for antiviral drug screens with SARS-CoV-2, lung adenocarcinoma Calu-3 and colon adenocarcinoma Caco-2 cell lines both lack robust endogenous AR expression, rendering screening results uninterpretable for AR-targeting drugs." (PMID 33310900, 2020). "Although the exact mechanism occurrence of prostate metastasis from lung adenocarcinoma remains unclear, possible explanations include vascular tropism through Batson’s plexus or interaction between EGFR and androgen receptor (AR) signaling pathways." (PMID 40740944, 2025). "For instance, JQ1 and OTX015 decrease SARS-CoV-2 infectivity and ACE2 levels in H1437 lung adenocarcinoma cells, but androgens and AR antagonists did not decrease ACE2 in this cell line." (PMID 33310900, 2020). "Treatment with AhR ligand benzo[α]pyrene (BaP) tremendously reduced constitutive AR expression as well as testosterone-induced AR protein levels in lung adenocarcinoma cells while TCDD did not reduce AR levels." (PMID 26154658, 2015).